LGI1 (leucine rich glioma inactivated 1)
Diseases named in the same sentence as LGI1 in open-access papers (continued):
Sharing a sentence is not in itself a finding about the gene and the disease.
autoimmune encephalitis (continued). "The predominance of left‐sided temporal involvement has also been reported in other neuroinflammatory diseases, such as optic neuritis, multiple sclerosis, and also in LGI1 autoimmune encephalitis." (PMID 41568938, 2026). "Anti-leucine-rich glioma-inactivated 1 antibodies were most commonly detected in patients with autoimmune encephalitis with ictal cold shiver (85.7 %)." (PMID 40958893, 2025). "The autoantibodies that were detected in patients with autoimmune encephalitis presenting with ictal cold shiver were anti-LGI1 and related antibodies." (PMID 40958893, 2025). "Clinical data of participants with leucine-rich glioma inactivated 1 autoimmune encephalitis (LGI1 AE)." (PMID 40470500, 2025). "LGI-1 autoimmune encephalitis belongs to a group of autoimmune encephalitides that target proteins associated with the voltage-gated potassium channel (VGKC) complex." (PMID 40904981, 2025). "Among the 87 patients diagnosed with anti-LGI1 antibody–positive autoimmune encephalitis, 62 were male (71.3%) and 25 were female (28.7%), yielding a male-to-female ratio of 2.48:1." (PMID 41473232, 2025). "Anti-leucine-rich glioma inactivated-1 (LGI1) autoimmune encephalitis (AE) is a type of AE characterized by seizures and cognitive, behavioral, and memory disturbances." (PMID 40470500, 2025). "Anti-leucine-rich glioma inactivated-1 (LGI1) and anti-contactin-associated-protein-2 (CASPR2) autoimmune encephalitis (AIE) are common and characterized by pathogenic antibodies targeting neuronal autoantigens." (PMID 40094812, 2025). "Viral infections are the most frequent known cause, followed by autoimmune encephalitis (e.g., anti-NMDA, LGI1, GABA, and AMPAR)." (PMID 41409353, 2025). "The metabolic signature of anti‐leucine‐rich glioma‐inactivated 1 (anti‐LGI1) autoimmune encephalitis remains poorly defined." (PMID 41399525, 2025). "LGI1‐antibody encephalitis (LGI1‐Ab‐E) is a common form of autoimmune encephalitis where most patients demonstrate ‘good’ clinician‐rated outcomes." (PMID 39996410, 2025). "Leucine-rich glioma inactivated 1 (LGI1) autoimmune encephalitis (AE) is characterized by seizures, as well as cognitive, memory, and behavioral disturbances." (PMID 40470500, 2025). "This further validates this model as an accurate representation of the clinical and electrophysiological human LGI1 autoimmune encephalitis phenotype." (PMID 39984135, 2025). "This significant correlation of hyponatremia with anti-LGI1 LE has prompted discussions advocating for the testing of autoimmune encephalitis in cases of patients presenting with seizures and subsequently being found to be hyponatremic." (PMID 39006729, 2024). "Our results have important implication for understanding the pathophysiology of LGI1 autoimmune encephalitis and the physiologic functions of LGI1." (PMID 39141878, 2024). "Anti-leucine-rich glioma-inactivated 1 limbic encephalitis (anti-LGI1 LE) is a type of autoimmune encephalitis that is distinctly characterized by neuropsychiatric changes, sleeping disturbances, and faciobrachial dystonic seizures (FBDS)." (PMID 39664290, 2024). "Eventually, the autoimmune encephalitis panel showed positivity to anti-LGI1 IgG antibodies, and a diagnosis of anti-LGI1 LE was established." (PMID 39664290, 2024). "Diagnosis was autoimmune encephalitis with antibodies against LGI1 (n = 4), CASPR2 (n = 4), the NMDA receptor (n = 3), and the GABAB receptor (n = 1)." (PMID 38862652, 2024). "First, the strong hypermetabolism in the bilateral basal ganglia in the FDG-PET is similar to those in patients with autoimmune encephalitis related to anti-LGI1 antibody." (PMID 38887352, 2024). "For the inflammatory category, this study contained 7 patients with autoimmune encephalitis associated with AMPA2, LGI1 or GABAB receptors." (PMID 36918794, 2023).
autoimmune encephalitis (continued). "Anti-leucine-rich glioma-inactivated 1 (LGI1) autoimmune encephalitis is characterized by cognitive dysfunction, mental disorders, faciobrachial dystonic seizures (FBDS), and hyponatremia." (PMID 37383232, 2023). "Anti-leucine-rich glioma-inactivated 1 (LGI-1) autoimmune encephalitis (AE), characterized by rapid decline of memory, seizures, and neuropsychiatric abnormalities, is a rare but devastating disorder." (PMID 40217477, 2023). "With the discovery of autoimmune encephalitis and the identification of autoantibodies targeting cell surface or synaptic proteins, the number of reported anti-LGI1 AE cases has increased exponentially." (PMID 40217477, 2023). "In this article, we describe a female patient with autoimmune encephalitis who tested positive for leucine-rich glioma inactivated 1 (LGI1) antibodies and had hippocampal inflammatory edema in the lesion area." (PMID 37539383, 2023). "A 48-year-old man was diagnosed with anti-leucine-rich glioma inactivated 1 (LGI1) autoimmune encephalitis after he developed fast cognitive deterioration and hyponatremia following his second dose of the BNT162b2 mRNA vaccine." (PMID 36851087, 2023). "There is retrospective evidence of case series in autoimmune encephalitis with LGI1 antibodies that steroids (intravenous, oral or both) are even superior to immunoglobulins applied intravenously in functional outcome terms." (PMID 36576564, 2023). "Yet, patients with LGI1 (the most common form of autoimmune encephalitis), CASPR2m and IgLON5 antibodies can present over long durations with minimal evidence of paraclinical investigation abnormalities, other than the autoantibody itself." (PMID 36441519, 2023). "Autoimmune encephalitis with autoantibodies to inactivated leucine-rich glioma 1 (LGI1) accounts for the diagnosis of anti-LGI1 autoimmune encephalitis." (PMID 37568953, 2023). "Anti-LGI1 AE now accounts for 11.2% of all autoimmune encephalitis cases, the latter of which is also the most common form of limbic encephalitis." (PMID 40217477, 2023). "The present work aimed to evaluate the effect of human anti-LGI1 antibodies from patients with autoimmune encephalitis on the emergence of seizures in rodent models." (PMID 36849262, 2023). "Subsequent to these results being obtained, the patient’s grandfather’s serum autoimmune encephalitis antibody test results were also found to be positive for LGI-1 and CASPR2 antibodies in serum." (PMID 37553563, 2023). "Anti-leucine-rich-glioma-inactivated 1 (LGI1) antibody autoimmune encephalitis is a rare autoimmune encephalitis." (PMID 36852369, 2023). "Nevertheless, the role of LGI1 in the regulation of the mature neuronal network has been recently highlighted by the description of autoimmune encephalitis with LGI1 auto-antibodies (Abs)." (PMID 35984846, 2022). "The patient was diagnosed anti-LGI1 antibody-mediated autoimmune encephalitis and treated with pulse methylprednisolone 1000 mg daily for 3 days, reduced by a half every 3 days." (PMID 35896991, 2022). "Some degree of cognitive impairment is the single most consistent finding in autoimmune encephalitis, such as those associated with autoantibodies targeting NMDAR, LGI-1, and GAD, among others." (PMID 36138865, 2022). "Alterations in specific gut microbiota were also reported in anti-leucine-rich glioma-inactivated 1 (anti-LGI1) autoimmune encephalitis patients." (PMID 35877424, 2022). "In this study, we show that using an IIF-CBA co-expressing LGI1 and ADAM23 all patients with LGI1 autoimmune encephalitis had LGI1 antibodies in CSF." (PMID 36591253, 2022). "In patients with suspected autoimmune encephalitis, the detection of several autoantibodies including LGI1 and thymomas provides useful information for making an accurate diagnosis." (PMID 35295746, 2022).
autoimmune encephalitis (continued). "Anti-leucine rich glioma inactivated 1 (LGI1) autoimmune encephalitis (AE) is characterized by cognitive impairment or rapid progressive dementia, psychiatric disorders, faciobrachial dystonic seizures (FBDS) and refractory hyponatremia." (PMID 35069602, 2022). "For that, antibodies for autoimmune encephalitis were tested, and the anti-LGI1 antibodies were positive in serum and cerebrospinal fluid." (PMID 33519701, 2021). "Represented in smaller but still significant numbers were other subgroups of autoimmune encephalitis with other antigenic targets including glycine receptor, LGi1, Caspr2, DPPX, GABA-B, IgLON5, GFAP, and SOX1." (PMID 33692738, 2021). "Anti leucine-rich glioma inactivated 1 (LGI1) limbic encephalitis (LE) is rare autoimmune encephalitis, characterized by acute or subacute cognitive impairment, faciobrachial dystonic seizures, mental disorders, and refractory hyponatremia." (PMID 34398024, 2021). "Anti‐leucine‐rich glioma‐inactivated 1 (LGI1) autoimmune encephalitis (AE) is characterized by complex manifestations of seizures." (PMID 34291554, 2021). "Antibody-LGI 1 autoimmune encephalitis (anti-LGI1 AE) has increasingly been recognized as a primary autoimmune disorder with favorable prognosis and response to treatment." (PMID 30732585, 2019). "Another mechanism may be potassium or calcium dysregulation, especially in the cases of autoimmune encephalitis associated with NMDA, LGI1, Casp2, AMPAR, or DPPX antibodies." (PMID 41598359, 2026). "LGI1-antibody encephalitis (LGI1-Ab-E) is a common form of late-onset autoimmune encephalitis." (PMID 39454566, 2025). "A retrospective analysis of nine serum and six CSF samples from patients with anti-LGI1 antibody-associated autoimmune encephalitis found no positivity for anti-ADAM23 antibodies, supporting its independent existence." (PMID 40519920, 2025). "In retrospect, his presenting symptoms should have been key evidence for autoimmune encephalitis, anti-LGI1 LE specifically, and a lumbar puncture should have been initiated earlier to start appropriate management and avoid this patient’s lengthy disease course." (PMID 39006729, 2024). "The autoimmune encephalitis panel returned and revealed positive anti-LGI1 IgG antibodies." (PMID 39006729, 2024). "However, in the case of suspected autoimmune encephalitis with anti-LGI1 and anti-CASPR2 antibodies in the elderly, the results of these tests should not lead to a decision to abandon the serum antineuronal antibody test." (PMID 37568953, 2023). "Therefore, the patient was diagnosed with anti-IgLON5 disease and anti-LGI1 autoimmune encephalitis." (PMID 37383232, 2023). "Autoimmune encephalitis related to the leucine-rich glioma-inactivated protein 1(LGI1) antibody is the most prevalent in older adults, manifesting as seizures, faciobrachial dystonic seizures (FBDS), cognitive impairment, memory disturbance, hyponatremia and neuropsychiatric disorders." (PMID 37391712, 2023). "Anti-leucine-rich glioma inactivated 1 (anti-LGI1) autoimmune encephalitis (AE) is a subset of antibody-related encephalitis manifesting clinically as subacute onset memory impairment, behavioral changes, and seizures including facial brachial dystonic seizures." (PMID 37264220, 2023). "Furthermore, our results lend support for the putative ameliorative effects of agents preventing auto-Ab-LGI1 interaction and GABAergic agonists in autoimmune encephalitis." (PMID 38035091, 2023). "Three patients with distinct forms of autoimmune encephalitis—anti-GABABR, anti-LGI1, and anti-NMDAR encephalitis—demonstrated rapid and sustained clinical improvement following efgartigimod treatment." (PMID 41462987, 2025). "In a retrospective series of 43 patients with thymoma and autoimmune encephalitis, only seven patients had either CASPR2 or LGI1 antibodies, and only two patients had co-occurrence of both antibodies." (PMID 40519393, 2025).
autoimmune encephalitis (continued). "First, the most frequent antibodies against autoimmune encephalitis, including AMPAR, LGI1, DPPX, Caspr2, and GABABR, were screened in 148 CSF samples from patients with schizophrenia using CBA." (PMID 38770306, 2024). "Eleven percent of patients (5/48) had autoimmune encephalitis, two NMDA (N-methyl-D-aspartate) antibody positive, two LG1 (leucine-rich glioma inactivated -1) antibody positive, and one GAD (anti-glutamic acid decarboxylase) antibody positive." (PMID 38288171, 2023). "Autoimmune encephalitis can also be induced by antibodies directed against gangliosides GQ1b, DPPX, CASPR2, and LGI1." (PMID 37568953, 2023). "Another recent study of 25 patients with autoimmune encephalitis (NMDAR, n = 10; LGI-1, n = 9; Caspr2, n = 3; both LGI1 and Caspr2, n = 1, GABA-bR, n = 1; AMPAR, n = 1), demonstrated elevated serum levels of NfL that correlated with elevated levels of CSF NfL." (PMID 35309573, 2022). "The main subtypes of autoimmune encephalitis were NMDAR-AE (61.35%), LGI-1-AE (20.61%), and GABAbR-AE (12.40%)." (PMID 33679765, 2021). "A study conducted in 2015 suggested that patients with AMPAR antibodies show less substantial recoveries than those with other types of autoimmune encephalitis [NMDAR, LGI1, or GABA(B)R]." (PMID 34054708, 2021). "While in autoimmune encephalitis with either CASPR2, LGI1, GABAA, or glycine receptor antibodies, CSF findings were generally normal." (PMID 34915865, 2021). "We contrast these cases with three patients examined during the same period whose eventual diagnosis was definite autoimmune encephalitis, supported by high titres of VGKC-complex/LGI1 antibodies." (PMID 25246643, 2015). "By contrast, three patients referred with possible prion disease had a clinical picture in keeping with autoimmune encephalitis and very high VGKC-complex/LGI1 antibodies." (PMID 25246643, 2015). "Plasma NfL and GFAP ratio of mean values in leucine-rich glioma inactivated 1 autoimmune encephalitis (LGI1 AE) vs. non-inflammatory controls." (PMID 40470500, 2025). "AE at the time of diagnosis when Plasma IL-1β and IL-10 ratio of mean values in leucine-rich glioma inactivated 1 autoimmune encephalitis (LGI1 AE) vs. non-inflammatory controls." (PMID 40470500, 2025). "The transfection cytology methods were used to detect autoimmune encephalitis antibodies (NMDAR, AMPAR1, AMPAR2, LGI1, CASPR2, GABABR, DPPX, IgLON5, GlyRα1, GABAARα1, GABAARβ3, mGluR1, mGluR5, D2R, Neurexin-3α, GAD65, KLHL11, gAChR, AQP4, MOG, GFAP) in CSF and serum." (PMID 40771880, 2025). "An autoimmune encephalitis panel by immunoblot was performed on serum and CSF, including surface antibodies (NMDA, LGI-1, CASPR2, AMPA, GABA-A, and GABA-B) and intracellular antibodies (Titin, SOX-1, Hu, Yo, Ri, Ma-2, CV-2, and amphiphysin) with negative result." (PMID 41409353, 2025). "Moreover, in about 62–75% of patients, antibodies characteristic of autoimmune encephalitis, such as anti-NMDAR, anti-GABAAR, anti-Caspr2, anti-LGi1, or anti-AMPAR, are found in the cerebrospinal fluid." (PMID 37568953, 2023). "The main message of our study is that the commercial IIFA for autoimmune encephalitis leads to false negative results in a substantial number of patients, especially when CSF is used, and predominantly for LGI1, GABABR and AMPAR antibodies." (PMID 34267758, 2021). "Six main types of antibodies are detected and used to diagnose autoimmune encephalitis in Chongqing, Southwestern China: anti-NMDA receptor antibody, anti-GABAB receptor antibody, anti-LGI1 antibody, anti-CASPR2 antibody, anti-AMPA1 receptor antibody, and anti-AMPA2 receptor antibody." (PMID 31781111, 2019). "LGI1 was also considered as a possible post-synaptic receptor for Caspr2 as it is recruited within the VGKC complex where it interacts with ADAM22 and ADAM23 and LGI1 is also involved in some autoimmune encephalitis." (PMID 26217189, 2015).
autoimmune encephalitis (continued). "In addition to these, serum autoimmune encephalitis (NMDA, CASPR-2, LGI-1, GABA-B, AMPA1, AMPA2), paraneoplastic (anti-GAD, Ma1/Ma2, CRMP-5, amphiphysin, Yo, PCA2, Hu, Ri) antibody panels and anti- were assessed in 21 and 19 patients respectively and all were negative." (PMID 37152622, 2023). "Another serum autoimmune encephalitis antibody test was performed before discharge and was positive for LGI-1 IgG antibodies (1:10 +) and negative for CASPR2 IgG antibodies (note: pre-diagnosis, was performed using a two-color fluorescent cytometric bead array assay)." (PMID 37553563, 2023). "The results of tests for antibodies associated with autoimmune encephalitis, such as NMDAR, LGI-1, and GAD, often take several days to come back, and may not be helpful in seronegative autoimmune cases, which are being recognised increasingly." (PMID 37611003, 2023). "Negative autoimmune encephalitis panel antibodies, including NMDA receptor, AMPA receptors 1 and 2, LGI1, anti-Ma2/Ta, anti-Hu, anti-Ri, anti-Yo, and anti-Zic4, ruled out paraneoplastic or autoimmune encephalitic syndromes." (PMID 40909059, 2025). "Extended panels of autoimmune encephalitis autoantibodies performed in rat brains by IHC were negative (anti-NMDAR, AMPAR, GABABR, GABAAR, LGI1, CASPR2, mGluR1, mGluR2, mGluR5, DPPX, IgLON5, Neurexin)." (PMID 40150045, 2025). "CSF testing using the Autoimmune Encephalitis Mosaic 6 kit (Euroimmun) was negative for all antibodies (NMDA receptor, AMPA receptor, GABA-B receptor, CASPR2, LGI1 and DPPX)." (PMID 36591253, 2022). "Extensive microbiological findings, including CSF PCR for herpes simplex virus (HSV) and varicella-zoster virus (VZV) and CSF cultures, as well as a comprehensive autoimmune encephalitis panel in serum and CSF (anti-NMDA, anti-AMPA, anti-GABA, anti-LGI1, anti-CASPR2, anti-DPPX), were all negative." (PMID 42005155, 2026). "However, anti-NMDA receptor antibodies were negative in blood and CSF, as were other antibodies for autoimmune encephalitis, including CASPR2 and LGI1." (PMID 34681037, 2021). "Although autoimmune encephalitis of any kind is ultimately not an ED diagnosis, it is crucial for the emergency physician to recognize this constellation of FDBS, hyponatremia, and worsening cognitive decline as being highly suspicious of anti-LGI-1 antibody LE." (PMID 34437034, 2021).